HCFC2 (host cell factor C2)
Synonyms: HCF-2; HCF2
Tractability: Antibody: its Gene Ontology location is reachable by antibodies, with high confidence. PROTAC: UniProt records ubiquitination sites on it; ubiquitination databases record sites on it.
Gene: Protein-coding gene on chromosome 12 (104,064,531 to 104,106,525, forward strand). Ensembl gene ENSG00000111727.
Subcellular location: Cytoplasm; Nucleus
Subcellular location (Human Protein Atlas): Nucleoplasm; Cytosol; Plasma membrane
Pathways (Reactome):
Gene expression (Transcription): Formation of WDR5-containing histone-modifying complexes
Gene Ontology:
Molecular function: protein binding; transcription coactivator activity; transcription coregulator activity
Biological process: chromatin remodeling; negative regulation of transcription by RNA polymerase II; regulation of DNA-templated transcription; regulation of transcription by RNA polymerase II; viral process; positive regulation of DNA-templated transcription
Cellular component: cytoplasm; cytosol; MLL1 complex; MLL1/2 complex; nucleoplasm; nucleus; Set1C/COMPASS complex; histone methyltransferase complex
Genetic constraint (gnomAD): Loss-of-function variants: 10 observed, 65.75 expected, observed/expected ratio (o/e) 0.15, 90% interval 0.093 to 0.26. The upper end of that interval is the gene's LOEUF score, 0.26, which puts it in group 1 of 6, group 1 being the genes least tolerant of losing a copy. Missense variants: 510 observed, 838.71 expected, observed/expected ratio (o/e) 0.61, 90% interval 0.56 to 0.65. Synonymous variants: 273 observed, 301.13 expected, observed/expected ratio (o/e) 0.91, 90% interval 0.82 to 1.
Homologues: Orthologues: chimpanzee HCFC2 (99% identical), macaque HCFC2 (98% identical), dog HCFC2 (95% identical), pig HCFC2 (94% identical), rabbit HCFC2 (94% identical), mouse Hcfc2 (82% identical), rat Hcfc2 (82% identical), guinea pig HCFC2 (75% identical), tropical clawed frog hcfc2 (58% identical), Drosophila melanogaster Hcf (42% identical), Caenorhabditis elegans hcf-1 (37% identical). Paralogues in human: HCFC1 (53% identical), FBXO42 (15% identical), LZTR1 (14% identical), KLHDC10 (13% identical), RABEPK (12% identical), KLHDC3 (12% identical), KLHDC1 (12% identical), KLHDC2 (12% identical), KLHDC4 (11% identical), KLHDC9 (8% identical).
Diseases named in the same sentence as HCFC2 in open-access papers:
HCFC2 is named in the same sentence as 3 diseases in open-access papers, as found by Europe PMC text mining. Sharing a sentence is not in itself a finding about the gene and the disease. The quoted sentences say what the papers report.
virus infection (1 paper, 2022). "HCFC2 (p-value 0.0395; protein: host cell factor C2) encodes one of two proteins which interact with VP16, a herpes simplex virus protein that initiates virus infection." (PMID 36038535, 2022).
tumor (1 paper, 2020). "There are limited studies of the tumor specific roles of HCFC2 and ZNF516, suggesting that additional studies are needed to elucidate their associations with LUAD." (PMID 33221751, 2020).
HCFC2 also shares sentences with these, for which no sentence is quoted: congenital heart defects (1 paper).